SOCAR (serous ovarian cancer associated RNA)
Gene: Long non-coding RNA gene on chromosome 2 (111,491,272 to 111,570,974, forward strand). Ensembl gene ENSG00000240350.
Diseases named in the same sentence as SOCAR in open-access papers:
SOCAR is named in the same sentence as 2 diseases in open-access papers, as found by Europe PMC text mining. Sharing a sentence is not in itself a finding about the gene and the disease. The quoted sentences say what the papers report.
glioblastoma (1 paper, 2023). The most malignant astrocytic tumor (WHO grade IV). "Eight genes, AC016737.2, BNC2-AS1, AC007040.1, AC009248.3, SOCAR, LAGE3, TOMM20L, and FP671120.11, were specific to patients with IDH1-wt and TERT-promoter-mutated glioblastoma." (PMID 37568598, 2023).
tumor (1 paper, 2023). "Additionally, MeRIP-qPCR assays validated that SOCAR and SNHG8 transcripts were hypermethylated, and PCAT19 and COLCA1 transcripts were hypomethylated in LUAD tumor tissues." (PMID 37029420, 2023).